C16orf86 (chromosome 16 open reading frame 86)
Synonyms: FLJ41802
Tractability: No criterion of Open Targets' tractability assessment is met for any kind of drug.
Gene: Protein-coding gene on chromosome 16 (67,666,814 to 67,668,757, forward strand). Ensembl gene ENSG00000159761.
Genetic constraint (gnomAD): Loss-of-function variants: 19 observed, 19.47 expected, observed/expected ratio (o/e) 0.98, 90% interval 0.68 to 1.43. The upper end of that interval is the gene's LOEUF score, 1.43, which puts it in group 5 of 6, group 1 being the genes least tolerant of losing a copy. Missense variants: 391 observed, 401.7 expected, observed/expected ratio (o/e) 0.97, 90% interval 0.89 to 1.06. Synonymous variants: 188 observed, 174.69 expected, observed/expected ratio (o/e) 1.08, 90% interval 0.95 to 1.22.
Homologues: Orthologues: chimpanzee C16H16orf86 (99% identical), macaque C20H16orf86 (93% identical), dog C16orf86 (71% identical), pig C16orf86 (70% identical), rabbit C16orf86 (63% identical), guinea pig C16orf86 (62% identical), mouse 4933405L10Rik (62% identical), rat C19h16orf86 (55% identical).
Diseases named in the same sentence as C16orf86 in open-access papers:
C16orf86 is named in the same sentence as 1 disease in open-access papers, as found by Europe PMC text mining. Sharing a sentence is not in itself a finding about the gene and the disease. The quoted sentences say what the papers report.
glioma (1 paper, 2022). A benign or malignant brain and spinal cord tumor that arises from glial cells (astrocytes, oligodendrocytes, ependymal cells). "Among them, PCOLCE2, ERP27, PSMD13, C14orf39, C16orf86, UGCG, and HPX were identified as prognostic factors for glioma for the first time." (PMID 35873494, 2022).